NLRP3 (NLR family pyrin domain containing 3)
Diseases named in the same sentence as NLRP3 in open-access papers (continued):
Sharing a sentence is not in itself a finding about the gene and the disease.
Fulminant hepatitis (12 papers, 2015 to 2025). Acute hepatitis complicated by acute liver failure with hepatic encephalopathy occurring less than 8 weeks after the onset of jaundice. "Previous studies have shown that abnormal activation of the NLRP3 inflammasome plays a crucial role in the acute inflammatory response in fulminant hepatitis (FH), and that inhibiting its activation can alleviate FH-induced liver injury and inflammation." (PMID 40521185, 2025). "In fact, REV-ERBα regulates the timing of NLRP3 expression and production of inflammatory cytokines by macrophages, reducing the severity of peritoneal inflammation and fulminant hepatitis." (PMID 36044097, 2022). "In vivo, RORγ inverse agonists render protective effects against sepsis and fulminant hepatitis in mouse models mediated by suppression of NLRP3 inflammasome." (PMID 33717162, 2021). "Nuclear receptor subfamily group D member 1 (NR1D1) protein has recently been described as reducing the circadian activity of the Nlrp3 inflammasome during fulminant hepatitis in mice." (PMID 31939051, 2020). "Nevertheless, the suppression of NLRP3 inflammasome has been demonstrated to decrease fulminant hepatitis and Zika virus replication but increase Newcastle virus replication." (PMID 30964929, 2019). "NLRP3 is a component of the inflammasome pathway that regulates maturation of the inflammatory cytokines interleukin (IL)-1b and IL-18, and in the absence of REV-ERBα, dysregulated expression of Nlrp3 leads to increased IL-1b and IL-18 and susceptibility to fulminant hepatitis." (PMID 39872076, 2022). "In mice, ablation of Rev-erbα led to exacerbated fulminant hepatitis, including increased liver damage that was blunted upon administration of the MCC950 specific NLRP3 inhibitor." (PMID 32849554, 2020). "At pathophysiological level REV-ERBα deficient mice displayed increased susceptibility to peritonitis and LPS/D-Galactosamine-induced fulminant hepatitis, whereas activation of REV-ERBα restrained the pathological conditions in an NLRP3 inflammasome-dependent manner." (PMID 33717162, 2021).
gastritis (12 papers, 2018 to 2025). Inflammation of the stomach. "The NLRP3 inflammasome activation and the IL-1β overexpression play crucial roles in the pathogenesis and development of Hp-associated gastritis." (PMID 36597090, 2023). "Together, our data identified that TRIM31 negatively regulated the activation of NLRP3 inflammasome in Hp-associated gastritis by affecting ROS and autophagy of gastric epithelial cells." (PMID 36597090, 2023). "Our data have demonstrated that the NLRP3 inflammasome was activated in Hp-associated gastritis in vivo and GES-1 cells with Hp infection in vitro." (PMID 36597090, 2023). "As the critical member of the NOD-like receptor signaling family, the NLRP3 inflammasome plays a crucial role in the pathogenesis of Hp-associated gastritis." (PMID 36597090, 2023). "The NLRP3 inflammasome activation is the molecular basis of Helicobacter pylori (Hp)-associated gastritis." (PMID 36597090, 2023). "In summary, the current study points out that TRIM31 attenuates NLRP3 inflammasome activation in Hp-associated gastritis by affecting ROS and autophagy." (PMID 36597090, 2023). "In this study, we further addressed Rabeprazole inhibited cell pyroptosis by destroying NLRP3 inflammasome, leading to decrease Caspase-1 activation and IL-1β and IL-18 release, and resulting in alleviating H. pylori-associated gastritis." (PMID 34266494, 2021). "Therefore, children with gastritis carrying NLRP3 rs10754558 polymorphism might have an increased risk for developing subclinical systemic inflammation, irrespective of the presence of H. pylori." (PMID 35204842, 2022). "H. pylori infection also resulted in upregulated NLRP3 and active caspase-1 expression in both gastritis and ulcer groups." (PMID 40563885, 2025). "Previous studies have revealed that MUC1 can inhibit NLRP3 inflammasome activation in Helicobacter pylori gastritis and bacterial infection, but they mainly studied NLRP3 inflammasome as an inflammatory mediator." (PMID 37880668, 2023). "In fact, MUC1 expression in macrophages limits gastritis through regulation of the NLRP3 inflammasome." (PMID 32230726, 2020). "Collectively, these studies demonstrate that targeted inhibition of the NLRP3 inflammasome represents a promising therapeutic strategy for the gastric inflammatory disorders investigated in these models, namely gastric ulcer and chronic atrophic gastritis." (PMID 40832584, 2025). "Similarly targeting the NLRP3 pathway, vitexin effectively alleviated 1-methyl-3-nitro-1-nitrosoguanidine-induced chronic atrophic gastritis." (PMID 40832584, 2025). "Regulation of NLRP3 inflammatory activity by MUC1 is critical for prevention of severe gastritis." (PMID 38463926, 2024). "NLRP3 inflammasome, which belongs to the family of nucleotide-binding and oligomerization domain-like receptors (NLRs), plays a critical role in the pathogenesis of H. pylori-related gastritis." (PMID 30524287, 2018). "However, the specific mechanism of the NLRP3 inflammasome activation in Hp-associated gastritis has not been fully elaborated." (PMID 36597090, 2023). "Similar to the findings in TLR2 rs380499 gene polymorphism, we also noticed a significant association between CC variant genotype of NLRP3 rs10754558 gene polymorphism and an increased number of circulating neutrophils in children with H. pylori-negative gastritis." (PMID 35204842, 2022). "In addition, we found a significantly higher value for eosinophils in children carrying the CC variant genotype of NLRP3 rs10754558 from H. pylori-induced gastritis compared with H. pylori-negative gastritis (p = 0.0365)." (PMID 35204842, 2022). "The significant association between CC genotype of NLRP3 rs10754558 polymorphism and ALT in children with H. pylori-negative gastritis suggests a possible susceptibility of these carriers to associate liver impairment in the context of gastric inflammation." (PMID 35204842, 2022).
gestational diabetes (12 papers, 2019 to 2025). Carbohydrate intolerance first diagnosed during pregnancy. "Recently, AS-IV has been reported to inhibit NLRP3 inflammatory body-mediated inflammation via TLR4/NF-κB/CaSR to improve vascular endothelial injury and attenuate gestational diabetes mellitus via targeting NLRP3 inflammasome in diabetic mice." (PMID 37261217, 2023). "In placenta and/or pancreatic tissues of patients and animal models with gestational diabetes (GDM), the expression of miR-222 and NLR family pyrin domain containing 3 (NLRP3) inflammasomes were up-regulated while C-X-C chemokine receptor type 4 (CXCR4) was downregulated." (PMID 34199293, 2021). "In addition, AsIV also reduced inflammatory genes IL-6 and TNF-α and suppressed NACHT, LRR, and PYD domain-containing protein 3 (NLRP3) inflammasome-related proteins in the pancreas of gestational diabetes mellitus (GDM) mice, leading to lower blood glucose and insulin levels." (PMID 41011612, 2025).
male infertility (12 papers, 2016 to 2025). The inability of the male to effect fertilization of an ovum after a specified period of unprotected intercourse. "A deeper understanding of the molecular mechanisms underlying NLRP-3 inflammasome activation will provide opportunities to develop strategies for preventing and treating diseases, including male infertility associated with the NLRP-3 inflammasome." (PMID 39712014, 2024). "Sertoli cells have been shown to generate IL-1β via NLRP3 inflammasome activation, and NLRP3 activation has been linked to male infertility in both preclinical and clinical studies, providing a potential mechanistic pathway that connects SD to impaired sperm parameters in humans." (PMID 41154744, 2025). "The results emphasized the regulatory role of JAK2/STAT3, NLRP3/Caspase-1 signaling in testicular tissue maintenance to resist PbAc-induced dysfunctions and male infertility." (PMID 40356721, 2025). "The importance of the inflammasome in male infertility is increasingly recognized, with NLRP-3 and IL-1 being identified as regulators of spermatogenesis." (PMID 39712014, 2024). "In this context, we discussed the NLRP3 inflammation, a multiprotein complex that initiates IL-1β–mediated inflammatory responses, and its relationship with male infertility." (PMID 37476898, 2023). "We planned this prospective randomized study to investigate this inflammasomal (NLRP3, IL1) mechanism in men with varicocele and/or azoospermia because it represents one of the important etiological causes of male infertility." (PMID 37476898, 2023). "They confirmed that NLRP3's sterile inflammation might be involved in the pathogenesis of male infertility." (PMID 39840312, 2024). "NLRP3 has been shown to be expressed in testicular spermatogonial cells (GC-1) and Sertoli cells (TM4), and its overexpression under infection or immune stress can lead to dyspermatogenesis and male infertility." (PMID 39840312, 2024).
mesothelioma (12 papers, 2012 to 2023). A usually malignant and aggressive neoplasm of the mesothelium which is often associated with exposure to asbestos. "In a separate study, silica and asbestos, the causal agent for asbestosis and mesothelioma, activated the NLRP3 inflammasome in macrophages, which required the efflux of the intracellular potassium and generation of intracellular reactive oxygen species." (PMID 36669831, 2023). "Our findings, being controversial with respect to another study on Italian patients, do suggest the need of further studies to unravel the contribution of NLRP1 and NLRP3 in susceptibility to mesothelioma." (PMID 26236392, 2015). "NLRP3 can promote the development of mesothelioma and is associated with lung metastasis." (PMID 36349316, 2022). "In this study we considered the hypothesis of an association between known NLRP3 single nucleotide variations and asbestos-induced mesothelioma." (PMID 23031505, 2012). "This suggests that NLRP3 priming is differentially regulated by ERK5 in this mesothelioma cell line." (PMID 29416614, 2018). "In this study we demonstrate that mesothelioma tumors/cells exhibit an attenuated NLRP3 inflammasome activation." (PMID 26689911, 2015). "The importance of the NLRP3 inflammasome and HMGB1 in asbestos-induced inflammation has in addition been linked to mesothelioma." (PMID 25406505, 2014). "This study proposes to evaluate the impact of known NLRP3 and NLRP1 polymorphisms in the individual susceptibility to asbestos-induced mesothelioma in subjects from a hyperendemic area for MM." (PMID 23031505, 2012). "Similarly, it has been shown that in mesothelioma tumors that exhibit attenuated NLRP3 inflammasome activation, doxorubicin and cisplatin activate the NLRP3/caspase-1 signaling pathway to activate pyroptosis and suppress tumor proliferation." (PMID 35883451, 2022). "Taken together, we speculated that NFE2L3, a novel biomarker in malignant pleural mesothelioma, can promote Th2 cell differentiation via IL-2/STAT5/NLRP3 signaling pathway in mesothelioma and many other cancers." (PMID 35664314, 2022). "While NLRP3 is critically involved in defense against microbial agents, defects in adequate NLRP3 control i.e., due to genetic mutations in NLRP3 results in auto-inflammatory diseases, and chronic NLRP3 stimulation induced by asbestos or silica drives chronic lung damage and promotes mesothelioma." (PMID 32751912, 2020). "For the present study, we hypothesize that NLRP3 inflammasome attenuation, which occurs in mesothelioma, enhances drug resistance, and hence there is a case for induction of inflammasome activation." (PMID 26689911, 2015). "Although NLRP3 SNPs was not involved in mesothelioma predisposition, these data proposed NLRP1 as a novel factor possibly involved in the development of mesothelioma." (PMID 23031505, 2012). "We analyzed NLRP3 rs35829419, rs10754558 SNPs and NLRP1 rs2670660, rs12150220 SNPs in 134 Italian patients with mesothelioma, in 256 healthy controls and in 101 individuals exposed to asbestos with no mesothelioma at the age of the enrollment." (PMID 23031505, 2012). "XMD8-92 inhibited doxorubicin-induced activation of the NLRP3 inflammasome in H2373 mesothelioma cells as depicted by the absence of caspase-1 p20 and IL-1β in the medium after XMD8-92 treatment." (PMID 29416614, 2018). "Moreover, they reveal that unlike macrophages and monocytes, and like MSTO-211H human mesothelioma cells, human mesothelial cells do not require exogenous TNFα or lipopolysaccharide to initiate NLRP3-mediated cytokine release." (PMID 23937860, 2013).
respiratory infections (12 papers, 2010 to 2026). "Our present study show that the pathogenic role of STING in respiratory infection also involves aberrant activation of NLRP3 inflammasome, an essential pathway critically implicated in inflammaging and age‐associated disorders." (PMID 35313074, 2022). "In the literature, there is evidence for both, a beneficial and detrimental role of mtROS during respiratory infections, also the activation of the NLRP3 inflammasome can be mediated by mtROS." (PMID 39543713, 2024). "During respiratory infections, the NLRP3 and AIM2 inflammasomes and caspase-11 protect against Brucella abortus through decreasing CFUs in the lungs and bronchoalveolar lavage fluid (BALF)." (PMID 35626718, 2022). "We therefore proceeded to assess the potential role of NLRP3 inflammasome in telomere‐related immunopathology during respiratory infection." (PMID 35313074, 2022). "Neutrophils have been recently shown to activate NLRP3 inflammasome upon respiratory infections which can be achieved via production of neutrophil extracellular traps." (PMID 33968032, 2021). "The activation of NLRP-3 was found to be a key modulator of respiratory infections and airway inflammation and the assembly of NLRP-3 components`triggers a pro-inflammatory cell death mode." (PMID 31112544, 2019). "Moreover, in vivo studies with respiratory infection of Staphylococcus aureus have demonstrated that neutralization of NLRP3 improves bacterial clearance, while blocking IL-1β/IL-18 does not." (PMID 36068223, 2022). "Furthermore, Nlrp3 activation depends on pneumolysin, which is required for the protection against respiratory infections with S. pneumonia." (PMID 32922370, 2020). "Furthermore, NLRP3 was required for protective immunity against respiratory infection with S. pneumoniae." (PMID 21085613, 2010). "Based on these findings, strategies to ameliorate the inflammatory pathology during respiratory infection such as COVID‐19 are now designed to target STING rather than the downstream NLRP3 for more health benefits." (PMID 35313074, 2022). "However, NLRP3 activation was required for PLY- and live S. pneumoniae-mediated enhancement of IL-1β secretion and NLRP3 was required for protection against respiratory infection with S. pneumoniae." (PMID 21085613, 2010). "For the first time, the observed inhibitory effect of GOS on NLRP3 inflammasome activation brings us one step closer to the understanding of the anti-inflammatory mechanism of GOS, which could be important for their beneficial effect on respiratory infections." (PMID 35777914, 2022). "Specifically, ZBP1 interactions with NLRP3 and AIM2 inflammasomes are described in the context of the bacteria and viruses such as Francisella novicida and influenza virus, indicating the importance of ZBP1 in host–pathogen interactions during respiratory infection." (PMID 35626718, 2022).
rheumatic diseases (12 papers, 2017 to 2025). "The NLRP3 inflammasome pathway has been associated with the IIR in multiple rheumatic diseases, including OA." (PMID 36829930, 2023). "Similar to other rheumatic diseases, canonical inflammasomes, including the NLRP3 inflammasome, are important players in SjS’s pathogenesis and progression." (PMID 38396768, 2024). "Emerging evidence has suggested an important role for the NLRP3 inflammasome in the pathogenesis of rheumatic diseases." (PMID 31775905, 2019).
Splenomegaly (12 papers, 2020 to 2026). Abnormal increased size of the spleen. "Immunisation of mice with alum, an agent that induces an inflammatory response primarily driven by NLRP3 inflammasome activation, caused splenomegaly and elevated splenic infiltration of inflammatory cells, which is reminiscent of the splenomegaly observed in XIAP deficient patients." (PMID 34222142, 2021). "Ectopic expression of EP364R in mice elicited significant upregulation of serum pro-inflammatory cytokines and splenomegaly, while its expression in bone marrow-derived macrophages (BMDMs) from NLRP3-knockout mice abrogated pyroptosis and related effects." (PMID 41739885, 2026). "Pharmacological blockade of NLRP3 in fully established disease leads to regression of thrombocytosis, splenomegaly and bone marrow fibrosis." (PMID 41298546, 2025). "NLRP3 is highly expressed in bone marrow cells from MPN patients, and its increased expression is associated with the JAK2V617F mutation, WBC counts and splenomegaly." (PMID 39188323, 2024). "We found that NLRP3-/- AML mice exhibited a milder splenomegaly and a lighter spleen weight compared to control AML mice." (PMID 34211462, 2021). "Consistent with this, splenomegaly was reduced in Jak2VF;Nlrp3−/− mice compared to Jak2VF mice." (PMID 41298546, 2025). "Importantly, NLRP3 inflammasome activation enhances bone marrow fibrosis and splenomegaly." (PMID 41298546, 2025). "The authors analyzed expression levels and genetic polymorphisms of inflammasome genes NLRP3, NF-KB, CARD8, IL1B, and IL18 on BM cells of MPN patients, demonstrating that an increased expression of NLRP3 inflammasome-related genes was associated with JAK2V617F mutation, WBC counts, and splenomegaly." (PMID 37760903, 2023). "Inhibition of the NLRP3 inflammasome or the downstream caspase-1 prevented MAS-mediated upregulation of IL-18 in the plasma but, interestingly, did not alleviate key features of hyperinflammatory disease including hyperferritinaemia and splenomegaly." (PMID 38775430, 2024). "Inhibition of the NLRP3 inflammasome, or downstream caspase-1, prevented MAS-mediated upregulation of plasma IL-18 but interestingly did not alleviate key features of hyperinflammatory disease including hyperferritinaemia and splenomegaly." (PMID 38464243, 2024). "However, in the CpG-induced model of MAS, NLRP3 and IL-18 were not required for the characteristic manifestations of hyperinflammation, including splenomegaly and hyperferritinaemia." (PMID 38775430, 2024). "Moreover, KrasG12D BM mice developed splenomegaly, which was not seen in KrasG12D; Nlrp3−/− BM mice." (PMID 32246016, 2020). "However, blockade of NLRP3, caspase-1 or IL-1 signalling was not sufficient to prevent the development of several features of hyperinflammatory disease, such as hyperferritinaemia and splenomegaly, suggesting that these traits occur independent of the NLRP3 inflammasome." (PMID 38775430, 2024).